SNHG19 (small nucleolar RNA host gene 19)
Synonyms: SNORD60HG
Gene: Long non-coding RNA gene on chromosome 16 (2,151,103 to 2,155,672, reverse strand). Ensembl gene ENSG00000260260.
Gene Ontology:
Biological process: RNA processing
Cellular component: nucleolus
Diseases named in the same sentence as SNHG19 in open-access papers:
SNHG19 is named in the same sentence as 9 diseases in open-access papers, as found by Europe PMC text mining. Sharing a sentence is not in itself a finding about the gene and the disease. The quoted sentences say what the papers report.
Alzheimer disease (1 paper, 2025). A progressive, neurodegenerative disease characterized by loss of function and death of nerve cells in several areas of the brain leading to loss of cognitive function such as memory and language. "In an in vitro Alzheimer’s disease (AD) model using SH-SY5Y cells, SNHG19 regulates the toxicity induced by beta-amyloid (Aβ) accumulation through interaction with hsa-miR-137." (PMID 40428349, 2025).
lung carcinoma (1 paper, 2025). "It has been reported that, upon stabilisation by Rab31 or SNHG19, ERK3 promotes EMT markers in cervical and lung cancers." (PMID 40936697, 2025).
osteoarthritis (1 paper, 2025). A noninflammatory degenerative joint disease occurring chiefly in older persons, characterized by degeneration of the articular cartilage, hypertrophy of bone at the margins and changes in the synovial membrane. "SNHG19 exerts its role in osteoarthritis by downregulating miR-34a through methylation, thereby inhibiting chondrocyte apoptosis." (PMID 40428349, 2025).
pancreatic cancer (1 paper, 2025). "Additionally, SNHG19 is aberrantly expressed in triple-negative breast cancer, pancreatic cancer, and other tumors." (PMID 40428349, 2025).
tumor (2 papers, 2025). "Further research, the downregulation of SNHG19 by siRNA treatment inhibits autophagy and promotes tumor cell apoptosis." (PMID 37282651, 2025).
cancer (1 paper, 2023). A tumor composed of atypical neoplastic, often pleomorphic cells that invade other tissues. "We also found a few novel lncRNAs such as LINC00940 and FLJ16779 that have not been reported earlier besides SNHG19, NPBWR1, and lncRNAs that are known to be involved in cancer and other diseases as well." (PMID 37218885, 2023).
SNHG19 also shares sentences with these, for which no sentence is quoted: breast carcinoma (1 paper); prostate carcinoma (1); triple-negative breast carcinoma (1).